INS (insulin)
Diseases named in the same sentence as INS in open-access papers (continued):
Sharing a sentence is not in itself a finding about the gene and the disease.
Insulin resistance (continued). "Insulin resistance describes the lack of activity of a known quantity of insulin (exogenous or endogenous) to promote the uptake of glucose and its utilization in an individual, as much as it does in metabolically normal individuals." (PMID 39415589, 2025). "INS: Insulin, HOMA‐IR: Homeostasis Model Assessment of Insulin Resistance, TG: Triglycerides, FBG: Fasting Blood Glucose, LDL‐C: Low‐Density Lipoprotein Cholesterol, BF%: Body Fat Percentage, VFG: Visceral Fat Grade, TFM: Trunk Fat Mass, TMM: Trunk Muscle Mass, SMM: Skeletal Muscle Mass." (PMID 40433895, 2025). "A recent study observed that suppression of glucose-induced postprandial GLP-1 occurred in adolescents with obesity and insulin resistance, but not in adolescents with obesity who were insulin sensitive." (PMID 41043686, 2025). "Furthermore, the insulin resistance as measured by HOMA-IR was significantly higher in the HS group (3.47 vs. 2.57, p = 0.016), and the insulin sensitivity as measured by HOMA-IS and QUICKI was significantly reduced in the HS patients (both p = 0.016)." (PMID 40217596, 2025). "It is characterized by the relative or absolute insufficiency of insulin secretion with or without concomitant insulin resistance, leading to high blood sugar levels." (PMID 40519490, 2025). "Therefore, our findings that a blunted response to insulin's effects on reducing FA mobilization was a primary predictor of impaired insulin‐mediated peripheral glucose uptake, suggests insulin resistance in aSAT may precede the development of insulin resistance in skeletal muscle." (PMID 39487600, 2025). "These patients also showed higher fasting glucose, insulin, cortisol levels, and increased insulin resistance as measured by Homeostatic Model Assessment of Insulin Resistance (HOMA-IR), independent of body composition or lifestyle variables​." (PMID 40635756, 2025). "Among sc-OSA patients, a significant improvement in insulin resistance was noted, although no significant changes were observed in fasting glucose or insulin levels." (PMID 40565316, 2025). "Basal insulin analogs mimic physiologic basal insulin secretion and reduce β-cell load; glucagon-like peptide-1 receptor agonists (GLP-1RA) can improve pancreatic β-cell function and reduce pancreatic β-cell apoptosis as well as improve insulin resistance." (PMID 39913436, 2025). "Our objective was to compare insulin and non-insulin-based indices of insulin resistance, together with advanced anthropometric and lipid markers, between prediabetes (PreDM) and type 2 diabetes (T2DM) and across hypertension grades in metabolic syndrome." (PMID 41465784, 2025). "It is characterized by impaired insulin secretion and insulin resistance, where the body will not fully respond to insulin." (PMID 40901275, 2025). "Mice with a liver-specific IDE knockout, fed a high-fat diet, developed worsened hepatic insulin resistance and glucose intolerance, but this did not affect insulin clearance compared with controls fed the same diet." (PMID 40985048, 2025). "ARO gene expression correlated positively with age, markers of obesity (eg, BMI, waist-hip ratio [WHR], body fat percentage), and markers of hyperglycemia and insulin resistance (eg, HbA1c, homeostatic model assessment of insulin resistance [HOMA-IR], fasting insulin) (P < .05)." (PMID 39833659, 2025). "Assessment of the insulin-associated index revealed that HOMA-IR values remained comparable across all the groups, suggesting a lack of insulin resistance." (PMID 41227734, 2025). "Group 1, which comprised lean participants, had the lowest C-peptide and insulin resistance, while group 2, comprising those metabolically non-obese, had higher visceral fat rating, C-peptide, and insulin resistance than those in group 1." (PMID 40995598, 2025). "Third, the absence of data on fasting insulin levels precludes the current comparison of the TyG index with other gold‐standard measures of insulin resistance." (PMID 41165399, 2025).
Insulin resistance (continued). "Because fasting glucose and insulin were not available before insulin therapy, Homeostasis Model Assessment of Insulin Resistance (HOMA-IR) was not calculated." (PMID 41393592, 2025). "Notably, these interventions led to decreases in fasting blood glucose (FBG) and homeostatic model assessment of insulin resistance (HOMA-IR), regulating insulin levels while increasing levels of catalase (CAT) and glutathione (GSH)." (PMID 40343290, 2025). "We showed that TAS1R3 mRNA and protein levels were depleted in T2D skeletal muscle, which was similarly observed in GLT-exposed human LHCN-M2 myotubes, which is used as a model for earlier stages of insulin resistance, suggesting that TAS1R3 levels are depleted in insulin-resistant muscle." (PMID 41515983, 2025). "The laboratory results showed that the patients with insulin resistance had significantly higher baseline markers of glucose metabolism, including fasting glucose levels and mean fasting insulin concentrations, compared to those without insulin resistance." (PMID 39941639, 2025). "Because fasting insulin and glucose were not collected in this study, we were unable to quantify insulin sensitivity (e.g., via Homeostatic Model Assessment for Insulin Resistance [HOMA-IR])." (PMID 40871721, 2025). "Insulin resistance is central in metabolic syndrome, but indices such as Homeostasis Model Assessment-estimated Insulin Resistance (HOMA-IR) require insulin assays that are costly and not always available." (PMID 41465784, 2025). "In their study, which included patients from 4 months onwards (median 4 years) after kidney transplantation, neither insulin release nor HOMA-2IR assessed insulin resistance changed in patients randomized to oral magnesium supplementation for 6 months." (PMID 39911868, 2025). "Brain insulin resistance is the process in which the quantity of insulin in the brain diminished or the brain cells do not respond to insulin." (PMID 40943177, 2025). "A recent study found that male rats subjected to 7 weeks of social isolation beginning on postnatal day 21 have an increased homeostatic model assessment for insulin resistance (HOMA‐IR) value, which indicates higher insulin resistance via measures of fasting blood glucose and insulin levels." (PMID 39821966, 2025). "As the skeletal muscle is the key metabolic organ involved in insulin-stimulated glucose utilization, sarcopenia promotes insulin resistance regardless of obesity status." (PMID 40284206, 2025). "Data from animal studies have shown that osteocalcin stimulates insulin secretion, as mice lacking osteocalcin developed reduced β-cell proliferation, glucose intolerance and insulin resistance." (PMID 40283231, 2025). "The insulin resistance is mediated by circumventing insulin-mediated Akt activation that usually phosphorylates FOXO and sequesters it in the cytoplasm; PERK phosphorylation of FOXO, however, relocates FOXO to the nucleus and promotes insulin resistance." (PMID 41301006, 2025). "Since adiponectin is an insulin-sensitizing hormone, reduced levels because of heightened TNF-α activity may further increase insulin resistance in GDM." (PMID 40722699, 2025). "The OGTT (Oral Glucose Tolerance Test), ITT (Insulin Tolerance Test), fasting blood glucose, random blood glucose, insulin levels, total triglyceride (TG), and total cholesterol (T-CHO) for the two models indicated abnormal glucose tolerance, insulin resistance and hyperlipidemia." (PMID 40384874, 2025). "Insulin resistance (IR) is a medical condition characterized by reduced cellular responsiveness to insulin, independent of hyperinsulinemia." (PMID 39881429, 2025). "It is possible that the amount of phosphatases in n-IR EVs is not sufficient enough to affect insulin signalling, whereas in IR EVs, the threshold is reached and they induce insulin resistance." (PMID 39422717, 2025).
Insulin resistance (continued). "Current research has focused on insulin and the homeostasis model assessment of insulin resistance (HOMA-IR) levels after rhGH therapy, rather than exploring the predictive value of baseline insulin and HOMA-IR in children with short stature for rhGH response." (PMID 41282298, 2025). "The most prevalent non-insulin-dependent DM is characterized by obesity, insulin secretory dysfunction, insulin resistance, and excessive glucose synthesis in the liver." (PMID 40787193, 2025). "The triglyceride–glucose (TyG) index, which has attracted attention in recent years as an index of insulin resistance that does not use insulin as a variable, was also evaluated." (PMID 40507147, 2025). "Metabolism‐related indicators were mainly monitored in this study including triglyceride (TG), HDL‐C, serum apolipoprotein A1 (ApoA1), serum apolipoprotein B (ApoB), fasting serum insulin (FINS), and homeostatic model assessment of insulin resistance (HOMA‐IR)." (PMID 41323197, 2025). "Furthermore, insulin levels and HOMA-IR values were significantly elevated in the model group compared to the NC group, indicating that T2DM mice have insulin resistance." (PMID 40271065, 2025). "Several studies have assessed insulin resistance using the Homeostatic Model Assessment of Insulin Resistance (HOMA-IR) and found that DM1 patients exhibit elevated fasting plasma insulin levels (i.e., hyperinsulinemia) and significantly higher HOMA-IR scores compared to healthy controls." (PMID 41018201, 2025). "Intervention with multiple probiotics causes a reduction in serum insulin levels and insulin resistance (HOMA-IR), without being correlated with the quantitative insulin sensitivity check index (QUICKI)." (PMID 40362845, 2025). "Dietary interventions such as low–glycemic-index (GI) diets have proven benefits: randomized trials show that low-GI regimens significantly lower fasting insulin and insulin resistance in PCOS, even without calorie restriction." (PMID 40694958, 2025). "The optimal model, designated as Model 5, was obtained by further including the effect of insulin resistance induced by high peripheral insulin and the biphasic effect (positive at low levels, negative at high levels) of lipids on beta-cell secretory capacity." (PMID 40568093, 2025). "Although both insulin resistance and β‐cell dysfunction are hallmarks of T2D, impaired insulin secretion is the culprit as insulin resistance alone does not result in T2D." (PMID 40898610, 2025). "Insulin resistance and T2DM result from the disruption of insulin signaling." (PMID 40076851, 2025). "Median (IQR) HOMA-IR values were 1.67 (1.21–1.94) in the insulin-resistant group and 0.48 (0.40–1.21) in the insulin-sensitive group (p = 0.136), showing a non-significant trend toward higher insulin resistance." (PMID 41300682, 2025). "Oxidative stress disrupts cellular homeostasis through several pathways: metabolically, it impairs insulin signaling and reduces glucose transporter 4 (GLUT4) activity, exacerbating hyperglycemia and insulin resistance, but can be mitigated by antioxidants like α-lipoic acid." (PMID 40667446, 2025). "Ectopic lipid accumulation triggers lipotoxicity, which is characterized by the release of FFAs and proinflammatory cytokines that impair insulin signaling by phosphorylating IRS-1 at serine residues; this leads to insulin resistance, which is a primary driver of type 2 DM." (PMID 41438998, 2025). "Conventional indices such as homeostatic model assessment of insulin resistance (HOMA-IR) and triglyceride-to-glucose index (TyG) rely on insulin or fasting glucose concentrations, which pose challenges for routine clinical implementation owing to variability, cost, and patient burden." (PMID 41465784, 2025). "Key proteins involved in insulin signaling, including the insulin receptor (IR), insulin receptor substrate (IRS), and phosphatidylinositol 3-kinase (PI3K), play critical roles in the development of insulin resistance." (PMID 40004236, 2025).
Insulin resistance (continued). "The homeostasis model of insulin resistance (HOMA-IR) evaluates IR and the pancreatic beta cell function, and the quantitative insulin sensitivity check index (QUICKI) which evaluates the ability of cells to respond to the effect of insulin, offer accessible and effective ways to determine IR." (PMID 40727914, 2025). "Although defined as hyperglycaemia, GDM reflects a widespread metabolic derangement secondary to increased insulin resistance with or without a deficit in insulin secretion." (PMID 41226805, 2025). "However, indirect effects via WC were associated with lower SBP (β = −0.69, p = 0.036) and DBP (β = −0.36, p = 0.041), improved insulin sensitivity (QUICKI: β = 0.0018, p = 0.044), and reduced insulin resistance (HOMA‐IR: β = −0.1099, p = 0.047)." (PMID 40969905, 2025). "Children and adolescents with obesity and insulin resistance have increased levels of fasting plasma glucagon and GLP-1, increased glucagon, and diminished GLP-1 responses during the OGTT, corresponding with reduced insulin sensitivity and β-cell function." (PMID 40649920, 2025). "Ninth, plasma insulin was not assessed, which precluded the calculation of insulin resistance indices such as HOMA-IR." (PMID 41465480, 2025). "Pregnancy is a state of insulin resistance where insulin’s response in target tissues, particularly (but not exclusively) muscle, liver, and fat, are modestly impaired." (PMID 40497429, 2025). "After 2 weeks of high-fed diet feeding, rats remained euglycemic due to compensatory insulin secretion, but with impaired insulin resistance index (ISI) and the homeostatic model assessment of insulin resistance (HOMA-IR), mimicking a pre-symptomatic disease state (insulin resistant, IR stage)." (PMID 40066372, 2025). "In contrast, white adipose tissue mass and adipocyte size were markedly reduced, accompanied by elevated circulating non-esterified fatty acid and insulin concentrations, indicating adipose tissue dysfunction and insulin resistance." (PMID 41282540, 2025). "Many previous studies have shown that obesity increases the risk of insulin resistance and T2DM, but not all individuals with obesity develop T2DM, and some maintain their insulin sensitivity and relatively normal metabolism." (PMID 40862130, 2025). "In some studies, chronic administration of rapamycin-induced insulin resistance or glucose intolerance without insulin resistance, but also insulin sensitization with glucose intolerance." (PMID 39859520, 2025). "In patients with obesity, insulin resistance can be triggered by WAT inflammation, as WAT inflammation leads to the release of pro-inflammatory cytokines, such as TNFα, IL-1β, IL-6, that inhibit insulin signaling and impaired glucose uptake." (PMID 40456448, 2025). "No significant data were found relating to insulin resistance (such as fasting insulin, HOMA-IR, or clamp-derived insulin sensitivity)." (PMID 41441014, 2025). "In this study we investigated the relationship between fasting plasma glucose (FPG), insulin levels, insulin resistance, and SUA levels in a non-diabetic older Finnish population." (PMID 40283451, 2025). "Insulin resistance arises from chronic nutrient overload, which activates inflammatory pathways including NF-κB and JNK in the liver, muscle, and adipose tissue, thereby impairing insulin signaling through serine phosphorylation of IRS-1." (PMID 40867531, 2025). "Among the various methods used to assess insulin resistance, the Homeostatic Model Assessment of Insulin Resistance (HOMA-IR) is a widely accepted and accessible surrogate, calculated using fasting plasma glucose (FPG) and insulin levels." (PMID 41003141, 2025). "In an animal model of hyperinsulinemia secondary to a high-fat diet (HFD), the insulin gene (Ins2 gene) deletion protected rats from obesity secondary to diet in the absence of hyperinsulinemia and insulin resistance." (PMID 40362446, 2025).
Insulin resistance (continued). "Insulin secretion as measured by fasting C-peptide was similar between participants with LTBI and controls (adjusted mean difference [95% CI], −0.05 nmol/L [−.18 to .09]; P = .51), as was insulin resistance measured by HOMA2-IR (−0.11 [−.38 to .15], P = .41)." (PMID 40242065, 2025). "Additionally, various biochemical parameters and metabolic markers, including c-peptide (p = 0.006) and insulin (p = 0.025) were elevated in people with OSA, suggesting insulin resistance." (PMID 41458545, 2025). "Obesity exacerbates testosterone deficiency in men and may induce insulin resistance; elevated insulin and insulin-like growth factor 1 (IGF-1) initially facilitate fat accumulation, but prolonged insulin resistance adversely affects muscle protein metabolism." (PMID 40718355, 2025). "The sensitivity analysis for insulin resistance that excluded participants who were taking insulin after randomisation (despite being randomised to the non-glargine groups; n=276/1321) yielded similar results." (PMID 39951058, 2025). "When the insulin signaling pathway is impaired, FGF21 enhances insulin signaling by activating the AMPK signaling pathway and inhibiting the mTOR signaling pathway to achieve glucose uptake and improve insulin resistance." (PMID 40881124, 2025). "Obese MASLD adolescents had marked metabolic dysfunction with higher insulin, homeostasis model assessment for insulin resistance, triglycerides, and liver enzymes compared to non-obese MASLD and controls." (PMID 39910885, 2025). "Most conventional insulin resistance metrics, including the Homeostatic Model Assessment (HOMA), Quantitative Insulin Sensitivity Check Index (QUICKI), and Matsuda Insulin Sensitivity Index (MATSUDA), are based on fasting plasma insulin levels." (PMID 39997933, 2025). "Chronic mTORC1 activation can disrupt insulin signaling by hyperactivating S6K1, which phosphorylates insulin receptor substrates on serine residues, impairing insulin signal transmission and promoting insulin resistance." (PMID 39796608, 2025). "As an anti-diabetic drug, DGF improves insulin resistance and controls blood glucose without increasing insulin secretion." (PMID 40397120, 2025). "Furthermore, children and adolescents with obesity and insulin resistance had elevated glucagon levels and diminished GLP-1 responses during the OGTT, in comparison to their counterparts with obesity and insulin sensitivity or those with normal weight." (PMID 40649920, 2025). "We acknowledge that insulin resistance was not evaluated through markers such as fasting insulin, glucose tolerance, or HOMA-IR." (PMID 40940373, 2025). "The pathogenesis of T2DM is insulin resistance and lack of insulin secretion, but genetic and environmental factors can also increase the risk of developing it." (PMID 40391012, 2025). "In humans and animal models, AGEs intake effects on insulin resistance remain controversial; indeed, other studies have not identified a relationship between habitual AGEs intake and insulin sensitivity." (PMID 40263184, 2025). "In addition, an in vivo animal study on Wistar rats treated with various doses of Pb for 32 days showed marginally elevated blood glucose levels, fasting insulin levels, and HOMA-IR, a tool to measure insulin resistance." (PMID 40408591, 2025). "The pathophysiological link between insulin resistance and hepatic steatosis is particularly robust, as insulin not only regulates glucose metabolism but also plays a vital role in lipid synthesis and degradation." (PMID 40002771, 2025). "In the three key insulin target tissues (skeletal muscle, liver, and white adipose tissue), AMPK phosphorylation is involved in gluconeogenesis and glycogen synthesis, which are impaired in insulin resistance." (PMID 40729355, 2025). "In contrast, cocultured adipocytes showed no significant increase in 2-NBDG uptake upon insulin stimulation, indicating the development of insulin resistance." (PMID 41157128, 2025).